MTOR (mechanistic target of rapamycin kinase)
Diseases named in the same sentence as MTOR in open-access papers (continued):
Sharing a sentence is not in itself a finding about the gene and the disease.
tumor (continued). "Factors in the TME, including pH, oxygen supply, immune surveillance, fibroblasts and ECM, can respond to drugs and initiate signalings to activate resistance-associated pathways in tumor cells, such as the AKT, mTOR, NF-κB, and STAT3 pathways." (PMID 30927928, 2019). "Recent research points at mTOR signaling hyper-activation and subsequent autophagy suppression as key events implicated in GBM stem cell maintenance, tumor propagation, as well as treatment resistance, which will be dealt with in the following sections." (PMID 31387280, 2019). "It is striking that all eight drugs show exactly the same trend towards neutrality with increasing tumour purity, including one of the current 2nd line treatments (the mTOR inhibitor temsirolimus)." (PMID 30792476, 2019). "Third, MAP3K7 expression was higher in tumor tissues, and high MAP3K7 expression, alone or in combination with its downstream regulator mTOR, was associated with poor survival in patients with HCC." (PMID 31214512, 2019). "The expression levels of hsa_circ_0037251 and miR-1229-3p were also detected in the removed tumours as well as that of mTOR." (PMID 31875034, 2019). "PDK1 signaling toward PLK1-MYC activation leads to tumor-initiating cell activation and resistance to mTOR inhibition." (PMID 31277692, 2019). "Our findings showed that autophagy inhibits tumor growth by suppressing the mTOR/p70S6K pathway, and previous studies confirmed the tumorigenic effect of autophagy using doxorubicin and cisplatin, which inhibit tumor growth." (PMID 31752184, 2019). "Altogether, these results show that the pharmacological inhibition of the EGFR/mTOR/HIF-1 axis has an effective anti-tumor activity in a resistant model of HNSCC cell line, in vitro and in vivo." (PMID 31640284, 2019). "Other studies have shown that it reduces tumor weight by targeting VEGFR2 through the Akt/mTOR/P70S6K signaling pathway." (PMID 30871059, 2019). "Upon hyperactivation, mTOR signaling promotes cell proliferation and metabolism that contribute to tumor initiation and progression." (PMID 30754640, 2019). "It is remarkable that mTOR alterations are bound to several tumor-extrinsic mechanisms that support tumor growth and mediate GBM relapse and infiltration." (PMID 31387280, 2019). "Because the role of DGKζ in carcinogenesis as well as in tumor progression has been poorly documented, only a few studies have reported that DGKζ has an anti-apoptotic function that is dependent on the mTOR pathway 28-31." (PMID 31523189, 2019). "Further, our results showed that GAS5 overexpression constrained cell proliferation, invasion, migration and tumor growth, and also induced apoptosis by regulating miR-106a-5p through the Akt/mTOR pathway." (PMID 31182630, 2019). "At the molecular level, AKT/c-MET tumor cells demonstrated high levels of activation of the AKT/mTOR and Ras/MAPK cascades." (PMID 31277283, 2019). "Mammalian target of rapamycin (mTOR) pathway is a key regulator of cellular metabolism and plays an important role in angiogenesis, cell growth and tumour proliferation." (PMID 30650598, 2019). "In fact, growing evidence shows that the mTOR signaling pathway plays an important role in the development androgen deprivation therapy resistance and stimulates tumor growth in the setting of castrated levels of testosterone." (PMID 31885728, 2019). "The p‐AKT3 and p‐mTOR proteins expression levels in isolated tumor tissues also were analyzed by immunohistochemical." (PMID 31207155, 2019). "Immunohistochemistry was performed to analyze components of the mTOR pathway, which was abnormally activated in tumor tissues." (PMID 31317677, 2019). "mTOR is a serine/threonine protein kinase that promotes tumour progression by regulating cancer cell survival and growth." (PMID 31052256, 2019).
tumor (continued). "Focusing on PD-1 and mTOR pathway, a network was built from the overexpressed genes, and their complexes known to be related to tumor progression using the Path Explorer tool in the IPA Path Designer." (PMID 31681332, 2019). "We found that a combination therapy targeting concurrently the Ras/MAPK and AKT/mTOR cascades is effective in inducing tumor growth restraint." (PMID 31277283, 2019). "LY3023414, a complex fused imidazoquinolinone, is an oral PI3K/mTOR and DNA-PK inhibitor that has anti-tumor effects in animal models." (PMID 31277692, 2019). "The interaction between the osteogenic cell and the tumor cell leads to the activation of mTOR in the tumor cell." (PMID 31766386, 2019). "These mice were treated with an mTOR inhibitor (rapamycin) that led to a significant decrease of pAkt and pS6, followed by an increase in the life span and a decrease in tumor growth, highlighting the crucial role of this pathway in LMS tumorigenesis." (PMID 31416195, 2019). "In vivo, treatment with OV alone or in combination with CDDP significantly reduced the tumor sphere-forming ability and decreased EV cargos containing mTOR, PI3K, STAT3, β-catenin, and miR-21-5p." (PMID 31878245, 2019). "Inhibition of mTOR would, therefore, prevent epithelial-mesenchymal transition and inhibit tumor cell dissemination." (PMID 31627299, 2019). "Although few patients shared similar tumor mutational profiles, common pathways in unresponsive cases included those of regulation of cell cycle progress, PI3K/Akt and mTOR signaling, EGFR tyrosine kinase inhibitor resistance." (PMID 31717320, 2019). "The results revealed significant upregulation of the expression of STAT3 and mTOR in the tumor tissues compared with the corresponding normal tissue." (PMID 31287013, 2019). "Collectively, intratumoral knockdown of circNRIP1 effectively reduced PDX tumour growth in BALB/c nude mice via downstream metabolism alterations mediated by the AKT/mTOR signalling pathway." (PMID 30717751, 2019). "In advanced solid tumors, a phase Ib clinical trial of combined MEK inhibitor (pimasertib) and PI3K/mTOR inhibitor (voxtalisib) had poor long-term tolerability and limited anti-tumor activity." (PMID 31817676, 2019). "Combined therapies with mTOR inhibitors and other pathway inhibitors or conventional therapies are under investigation in preclinical and clinical trials in different tumor types." (PMID 30754640, 2019). "Recent studies prove that this compound is also able to inhibit tumor growth in mouse breast xenograft models derived from PI3K/Akt/mTOR pathway-dysregulated cell lines (MDA-MB-453 and JIMT-1)." (PMID 30123135, 2018). "This study also confirmed previous low-throughput studies on the frequent mutation of MEN1, and identified PTEN, another gene of the PI3K/mTOR pathway involved in the inhibition of PI3K, as a recurrently (7.3%) mutated tumour suppressor." (PMID 29321190, 2018). "Our study also demonstrates that over-activated CMA by SNX10 deficiency was responsible for the upregulated amino-acid metabolism and mTOR signaling activation; eventually promoted the abnormal growth and proliferation of tumor cells." (PMID 29867114, 2018). "Our results suggest that co-targeting metabolic pathways had tumour cell dependent additive/synergistic effects related to mTOR and metabolic protein expression patterns cell line dependently." (PMID 30574020, 2018). "Among them, we paid special attention to the amino-acid metabolism because it has been closely connected with mTOR signaling activation and tumor development." (PMID 29867114, 2018). "We have shown that propranolol-mediated perturbations in mitochondrial metabolism sensitize tumor cells to glucose deprivation, and that tumor cell metabolism and mTOR signaling are attenuated when propranolol is combined with the glycolytic inhibitor DCA." (PMID 30513596, 2018).
tumor (continued). "By a mechanistic point of view, Akt/mTOR and Erk and Creb intracellular pathways, known to be pivotal in the induction of tumor growth and survival, appeared modulated as consequence of TKIs/HLSC-EVs co-administration." (PMID 30546834, 2018). "Metformin is able to not only reduce insulin but also inhibit the mammalian target of rapamycin (mTOR) signaling pathway, which makes it an especially appealing target for evaluating metabolism unique to tumor cells, such as the Warburg effect." (PMID 30442142, 2018). "Recent studies have shown that miR-451 regulates downstream molecules including AMPK/CAB39/MARK and mTOR to determine the balance between rapid proliferation and invasion in response to metabolic stress in the harsh tumor microenvironment." (PMID 30286133, 2018). "Abnormal expression of PTEN leads to activation of the PI3K/AKT pathway, which up-regulates expression of mTOR, promotes proliferation of tumour cells, inhibits cell apoptosis and mediates multi-drug resistance of cells through PTEN/PI3K/AKT/mTOR." (PMID 30123092, 2018). "Although many studies have suggested that the AMPK/mTOR axis has a key role in anti-tumor mechanisms of metformin, our results showed that mTOR suppression by metformin is only partly dependent on AMPK activation." (PMID 29416762, 2018). "HGF/MET autocrine loop activity can lead to the overexpression of Bcl‐2 and mTOR, which inhibit the translation initiation factor eIF2 alpha, making the tumor cells resistant to both autophagy and apoptosis." (PMID 29282893, 2018). "Extensive immunohistochemical analyses were used to demonstrate the apparent effects of combined treatments on tumor architecture, vasculature, apoptosis, and the mTOR-pathway." (PMID 30087612, 2018). "Activation status of the RAS and phosphatidylinositol 3-kinase (PI3K)/AKT/mTOR pathways was assessed by DNA sequencing and immunohistochemistry on archival tumour tissue." (PMID 29527009, 2018). "Second, the AMPK pathway targets many key tumour-promoting signalling pathways, one of which is the mammalian target of rapamycin (mTOR)." (PMID 29515798, 2018). "The reduced tumor volume after treatment with mTOR inhibitors was already shown in in GEO (KRASG12A; both OSI027 and Rapamycin), SW480 (KRASG12V; Rapamycin), LS174T (KRASG12D; Rapamycin) and HT29 (BRAFV600E) xenografts." (PMID 29907857, 2018). "The activation of LKB1 and AMPK ultimately lead to the inhibition of the mammalian target of rapamycin (mTOR) pathway that mediates anti-tumor activity of metformin." (PMID 30651935, 2018). "These LDs, as well as Torin-1, a potent mTOR inhibitor, blocked mTORC1 kinase activity in all three human tumor cell lines as evident from the significantly reduced levels of p70-S6K phosphorylation." (PMID 30546014, 2018). "Tuberous sclerosis complex 1 (TSC1), TSC2, and PTEN (phosphatase and tensin homolog) tumor suppressors are major negative regulators of mTOR signaling pathway." (PMID 29362480, 2018). "In patients with hepatocellular carcinoma the effect was much less convincing and especially in advanced stages of tumor disease overall and recurrence free survival remained unaffected by mTOR-Is." (PMID 29659588, 2018). "With the development of cytobiology, accumulating studies have shown that the PI3K/mTOR signaling pathway is frequently disregarded in most tumor cells, leading to malignant proliferation of normal organism cells." (PMID 29954109, 2018). "We identified six patients with metastatic RCC who initially responded to mTOR inhibitor therapy and then progressed, and had pre-treatment and post-treatment tumor samples available for analysis." (PMID 30256787, 2018). "We show that everolimus combined to olaparib lead to unrepaired DNA damage and tumor regression in vivo, through a cross-talk between DNA repair and mTOR pathways." (PMID 30038706, 2018).
tumor (continued). "We demonstrate for the first time that EpCAM is involved in tumour growth, chemo−/radiotherapy response and associated with activation of the PI3K/Akt/mTOR signalling pathway in CaP animal models in vivo." (PMID 30419852, 2018). "Recent evidence suggests that SEMA3F functions as a PI3K-Akt-mTOR inhibitor in mammalian cells, including T cells, ECs, and tumor cells." (PMID 30532711, 2018). "Several studies in mouse models have demonstrated that the expression of these two ectonucleotidases leads to tumor cells’ evasion from cytotoxic T cells responses, and that mTOR plays a critical role in the regulation of the CD39/CD73 expression." (PMID 30126252, 2018). "Based on the in vitro activity, it is expected that duvelisib in combination with dexamethasone, ibrutinib, or the mTOR inhibitor everolimus, would show enhanced tumor growth inhibitory activity compared to the effect of single agents." (PMID 30067771, 2018). "Signal transduction of PIK3CA via the kinases AKT and mTOR has been well documented in tumor growth and angiogenesis." (PMID 29985963, 2018). "Inhibition of Akt using MK2206 led to a significant inhibition of tumour growth during the treatment and local inhibition of phospho-mTOR, a key downstream effector of Akt signal." (PMID 30337563, 2018). "Our group demonstrated that the activation of PI3K/AKT/mTOR inhibits iodide uptake by diminishing sodium/iodide symporter transporter (NIS) expression in non-tumor cells." (PMID 29629339, 2018). "Due to frequent aberration of upstream proto-oncogenes and tumor suppressors, hyperactive mammalian/mechanistic target of rapamycin (mTOR) is a potent inducer of the Warburg effect." (PMID 29362480, 2018). "IL-6 and CSF-1 also induce mTOR activation, resulting in cell survival and growth of alternatively activated macrophages in the tumor microenvironment." (PMID 29422647, 2018). "Our results suggest that tumor progression is decreased by inhibition of the Akt/HIF‐2α/VEGF/mTOR pathway." (PMID 30107094, 2018). "Many small molecule tyrosine kinase inhibitors such as gefitinib, erlotinib, and dasatinib induced autophagy and suppressed mTOR signalling, indicating that an increase in autophagy suppresses tumour growth in vitro and in vivo." (PMID 29996471, 2018). "Overall, SEMA3F is a secreted physiological mTOR inhibitor that functions to inhibit tumor growth, angiogenesis, and metastasis." (PMID 30532711, 2018). "In support to this proposed model, combination of mTOR inhibitors and PD-1 antibody provided more durable and synergistic tumor regression than either single agent alone, each of which presented only modest efficacy." (PMID 30105035, 2018). "Autophagy has an important role in tumor development, and the constitutive activation of the PI3K/AKT/mTOR pathway is a hallmark of numerous tumors and has been reported to suppress the autophagy pathway." (PMID 29692710, 2018). "The eIF4E/4E-BP1 ratio is a key determinant of cell response to mTOR inhibitors as tumour cells with a high eIF4E/4E-BP1 ratio exhibit low sensitivity to asTORi-induced cell proliferation arrest." (PMID 30138450, 2018). "In vivo results showed that combination of Vismodegib and BEZ235 or their combination with cisplatin, significantly delayed MB tumor growth and increased survival of xenografted mice by targeting HH and mTOR pathways." (PMID 29682173, 2018). "OTUD7B (also called Cezanne-1) is a typical member of the subfamily of OTU DUBs29,30 and has been documented to regulate T-cell activation and tumor development by NF-κB, mTOR, or hypoxia signaling." (PMID 30405104, 2018). "Here, we examined ALK, MET and mTOR as potential therapeutic targets and determined the combinatorial efficacy of ALK and mTOR targeting on tumor cell growth in vivo." (PMID 29755689, 2018). "We suggested that Ru inhibited tumor angiogenesis by blocking the Akt/mTOR/p70S6K signaling pathway." (PMID 30111763, 2018).
tumor (continued). "Preclinical data demonstrates that inhibition of PI3K, Akt, and mTOR via molecular antagonists reduces tumor growth and proliferation in murine models." (PMID 30101126, 2018). "The ALK/MET inhibitor crizotinib enhanced the anti-tumor effect of the mTOR-inhibitor rapamycin in a patient-derived MPM xenograft with co-activated ALK/mTOR: combined therapy achieved tumor shrinkage in 4/5 tumors and growth stagnation in one tumor." (PMID 29755689, 2018). "In preclinical studies, a catalytic mTOR inhibitor was much more effective than rapamycin in yielding tumor cell apoptosis when combined with an autophagy inhibitor." (PMID 30013478, 2018). "It is actually known that the PI3K/mTOR inhibitors have an important immunomodulatory impact on the tumor microenvironment and angiogenesis." (PMID 30126252, 2018). "Concluding that TNBC and HER2 overexpression showed the highest cell proliferation and survival in a hypoxic tumor environment by activation of the mTOR pathway and HIF-1α stabilization via DDIT4 downregulation." (PMID 29707520, 2018). "The PI3K/AKT/mTOR pathway and its downstream 70-kDa ribosomal S6 kinase (p70S6K) are constitutively activated in human tumor cells, providing unique opportunities for therapeutic intervention." (PMID 30423811, 2018). "Functional coupling of SLC1A5 and SLC7A5 was observed in HeLa cells by transport and efflux of extracellular glutamine as a substrate for leucine uptake and mTOR activation, which are important for tumor cell growth." (PMID 29562706, 2018). "Mutations in the tumour suppressor genes TSC1 and TSC2 are well-described activating mutations in the kinase domain of the mTOR pathway." (PMID 30220708, 2018). "Aberrant activation of PI3K/Akt/mTOR is recognized to play a pivotal role in modulating cell proliferation and apoptosis especially in tumor progress." (PMID 30442873, 2018). "First, we have suggested that signaling pathways or nodes, other than mTOR, that induce EMT in tumor cells do so as a result of their cross-talk with mTOR." (PMID 30013478, 2018). "Dysregulated PI3K/Akt/mTOR signaling is involved in tumor cell growth, proliferation, apoptosis, survival, invasion, and metastasis." (PMID 29416003, 2018). "Fangchinoline was also observed to have an inhibitory effect on important oncogenic pathways (FAK, MEK-ERK1/2, NF-κB, PI3K-Akt-mTOR) in diverse tumor cells." (PMID 30301146, 2018). "PTEN (cytoband 10q23.31) has been identified as a tumour suppressor which inhibits the PI3K/Akt/mTOR signalling pathways." (PMID 29545918, 2018). "Increasing evidence indicates that inhibition of PI3K/Akt/mTOR pathway suppresses cell growth in many tumor types." (PMID 30390677, 2018). "Immunohistochemistry revealed decreased TSC2 protein content and increased phospho-S6 in the tumor cells, demonstrating mTOR pathway activation." (PMID 29764404, 2018). "The mammalian target of rapamycin (mTOR) pathway regulates major processes by integrating a variety of exogenous cues, including diverse environmental inputs in the tumor microenvironment (TME)." (PMID 30126252, 2018). "In GC cells, HAGLROS and mTOR levels are consistently parallel, with increased levels inhibiting autophagy and promoting tumor proliferation and invasion." (PMID 29329543, 2018). "The mTOR pathway modulates the interactions between the stroma and the tumor, thereby affecting both the tumor immunity and angiogenesis." (PMID 30126252, 2018). "It appears that only phosphorylated-S6K is a robust marker for detection of mTOR activity in tumor samples by at least two techniques including IHC, while the others molecules failed to be detected by IHC." (PMID 30564554, 2018).